METTL3 (methyltransferase 3, N6-adenosine-methyltransferase complex catalytic subunit)
Diseases named in the same sentence as METTL3 in open-access papers (continued):
Sharing a sentence is not in itself a finding about the gene and the disease.
Parkinson disease (3 papers, 2023 to 2026). A progressive degenerative disorder of the central nervous system characterized by loss of dopamine producing neurons in the substantia nigra and the presence of Lewy bodies in the substantia nigra and locus coeruleus. "Dopamine transporter-specific METTL3 knockout mice recapitulate m6A hypomethylation, neurodegeneration, and levodopa-responsive parkinsonism." (PMID 41842966, 2026). "Aberrant expressions of METTL3 and FTO have been associated with Alzheimer’s or Parkinson’s disease." (PMID 37990254, 2023). "NRF1 promotes m6A modification and IGF2BP2‐dependent stability of GLRX mRNA by increasing the expression of METTL3 and leads to the increase of GLRX expression, thus alleviating motor dysfunction and dopamine neuron degeneration in Parkinson's disease mice." (PMID 37735974, 2024).
proliferative vitreoretinopathy (3 papers, 2021 to 2023). Vitreoretinal membrane shrinkage or contraction secondary to the proliferation of primarily retinal pigment epithelial cells and glial cells, particularly fibrous astrocytes, followed by membrane formation. "METTL3 reduced cell proliferation through inducing cell cycle arrest at G0/G1 phase to attenuate proliferative vitreoretinopathy." (PMID 37559091, 2023). "Our data uncovered the critical function of METTL3 in regulation of proliferative vitreoretinopathy, and the elucidation of this regulatory mechanism will provide new ideas for the treatment of PVR." (PMID 33759344, 2021). "However, little is known about the role of METTL3 in these processes, and even less is known about the relationship between METTL3 and proliferative vitreoretinopathy (PVR)." (PMID 33759344, 2021).
prostate adenocarcinoma (3 papers, 2022). "While CNA were rare in primary prostate adenocarcinoma samples (~1% of cases), METTL3 CNA were more common in metastatic adenocarcinoma samples (~3% of cases), and NEPC (~17% of cases)." (PMID 36291932, 2022). "A comparative analysis of genetic alterations in METTL3, METTL14, WTAP and CBLL1 in primary prostate adenocarcinoma and metastatic PCa patients was undertaken." (PMID 36733939, 2022). "Expression and sub-cellular localisation of METTL3, METTL14, WTAP and CBLL1 were confirmed using IHC in both non-malignant and primary prostate adenocarcinoma specimens." (PMID 36733939, 2022). "Analysis of publicly available PCa patient datasets identified that METTL3 and WTAP expression was higher in primary prostate adenocarcinoma than in non-malignant prostate tissue, whereas conversely, METTL14 expression was found to be significantly lower." (PMID 36733939, 2022). "It was found that METTL3 (p < .0001) and WTAP (p < .01) expression were significantly higher in primary prostate adenocarcinoma patient samples compared with non-malignant prostate tissue, whereas METTL14 expression was significantly lower (p < .01) in tumour compared with non-malignant tissue." (PMID 36733939, 2022).
prostate tumor (3 papers, 2021 to 2024). "Methiltransferase-like 3 (METTL3) promoted by miR-146a-3p favors apoptosis and inhibits prostate tumor growth in nude mice." (PMID 38790213, 2024). "Seven regulators, including IGF2BP2, METTL3, METTL16, ZNF217, ZC3H13, RBM15B, and PRRC2A, exhibited significant correlations between CNVs and gene expression levels in prostate tumors." (PMID 34899855, 2021).
Ureteral obstruction (3 papers, 2021 to 2025). Obstruction of the flow of urine through the ureter. "The protein levels of N-Cad, α-SMA, and ZEB2 were increased in the 14-day unilateral ureteral obstruction (UUO 14 days) model and were decreased by the deletion of METTL3." (PMID 39059495, 2024). "However, in an animal model of AKI induced by unilateral ureteral obstruction (UUO) operation, m6A methylation in adult mouse kidneys was found to decrease and showed a similar change of the expressions of Mettl3 and Mettl14." (PMID 34307448, 2021).
uveal melanoma (3 papers, 2021 to 2022). A melanoma derived from melanocytes of the uveal tract. "In uveal melanoma, the expression of the main m6A regulatory enzyme METTL3 is found to be significantly increased." (PMID 35693795, 2022). "The knockdown of METTL3 prominently suppresses cell proliferation, colony formation, migration, and invasion via the downregulation of c-Met, indicating that METTL3 is a promising target for the treatment of uveal melanoma." (PMID 35693795, 2022). "In contrast, a study of uveal melanoma showed the opposite results, reporting upregulation of both m6A modifications and METTL3 and highlighting their role as cancer-promoting factors." (PMID 35117988, 2021).
adenoma (2 papers, 2020 to 2022). A neoplasm arising from the epithelium. "In the present study, we verified the m6A and METTL3 levels in both adenomas (precancerous lesions of CRC) and CRC tissues, and clarified the function of METTL3 in CRC progression." (PMID 35012593, 2022). "Adenoma and CRC samples were examined to detect m6A and METTL3 levels, and tissue microarrays were performed to evaluate the association of m6A and METTL3 levels with the survival of patients with CRC." (PMID 35012593, 2022). "M6A modification is regulated by RNA methyltransferase and demethylase, hence we assessed the expression of methyltransferase (METTL3, METTL14 and WTAP) and demethylase (FTO and ALKBH5) in both adenoma and CRC." (PMID 35012593, 2022). "The results indicated that the protein level of METTL3 was significantly higher in the CRC group relative to the normal and adenoma groups; this finding is consistent with the results in the database." (PMID 35012593, 2022).
adenovirus infection (2 papers, 2020). "As expected, Cre adenovirus infection caused the deletion of Mettl3 in primary brown adipocytes." (PMID 32245957, 2020). "When we assessed viral genome amplification by qPCR, we detected only a minimal change after knockdown of METTL3 or METTL14, indicating m6A is not required for early stage adenovirus infection." (PMID 33243990, 2020).
alcohol abuse (2 papers, 2023 to 2025). The use of alcoholic beverages to excess, either on individual occasions ("binge drinking") or as a regular practice. "Recent study demonstrated that Mettl3-mediated m6A modification plays a crucial role in metabolism disorders such as alcohol use disorder." (PMID 40666518, 2025).
alcoholism (2 papers, 2018 to 2023). "KEGG pathway analysis of genes up‐regulated by METTL3 depletion showed that the significant pathways were alcoholism and human T‐lymphotropic virus type 1 (HTLV‐I) infection." (PMID 29502358, 2018).
anaplastic thyroid cancer (2 papers, 2022 to 2024). "Furthermore, by silencing METTL3, which is the main player in the RNA methylation machinery, it was possible to evaluate the impact of m6A modification on gene expression in an anaplastic thyroid cancer model." (PMID 36232810, 2022). "Moreover, overexpressing METTL3 promoted the sensitivity of PTC and anaplastic thyroid cancer (ATC) cells to chemotherapeutic drugs and iodine-131 (131I) administration." (PMID 38993572, 2024). "Instead, the results of this study demonstrate how METTL3 down-regulation results in decreased ATC cell viability, suggesting how this component of the RNA methylation machinery plays a favorable role in the development, progression, and maintenance of anaplastic thyroid cancer." (PMID 36232810, 2022).
aneurysm (2 papers, 2024 to 2025). Bulging or ballooning in an area of an artery secondary to arterial wall weakening. "Additionally, levels of m6A modification and the expression of METTL3 and METTL14 are heightened in the aortic wall tissues affected by AAA, indicating a significant association with Ang II-induced aneurysm formation." (PMID 39834386, 2024).
aortic aneurysm (2 papers, 2021 to 2026). A ruptured aneurysm located in the wall of the proximal portion of the descending aorta proceeding from the arch of the aorta. "Similarly, we obtained the RNA‐seq data of m6A regulators Ythdc1 and Mettl3 from RNA‐seq public database (GEO number: GSE140947), and found that mRNA expression of Ythdc1 and Mettl3 is also upregulated in VSMCs of human aortic aneurysm sample." (PMID 41317401, 2026).
Arthritis (2 papers, 2022 to 2023). Inflammation of a joint. "A recent study showed that METTL3 can promote activation and inflammation in FLSs and the adjuvant-induced arthritis animal model using nuclear factor (NF)-κB signaling pathway." (PMID 35401168, 2022).
Azoospermia (2 papers, 2024 to 2025). Absence of any measurable level of sperm,whereby spermatozoa cannot be observed even after centrifugation of the semen pellet. "To further investigate whether m6A modification regulates L1 retrotransposons in men with meiotic arrest, a subtype of nonobstructive azoospermia, we detected the RNA expression of METTL3 and L1 in their seminal plasma." (PMID 38363375, 2024). "The frequency of underdeveloped gonads and incomplete germline development phenotypes increased by simultaneous knockdown of Smed-METTL3 and Smed-METTL14 (METTL3;METTL14(RNAi)), resulting in 85 % of the ovaries lacking oocytes and 71 % of samples with azoospermia." (PMID 41322074, 2025).
Brain Injuries (2 papers, 2023 to 2025). "Beyond regulating normal physiological processes of the nervous system, METTL3 is also involved in the regulation of various pathological events that occur in the nervous system, including brain tumors, neurodegenerative diseases, and brain injuries." (PMID 37189411, 2023). "Various studies have indicated the involvement of METTL3 in brain injuries." (PMID 37189411, 2023).
Brain Tumors (2 papers, 2017 to 2023). "KD of METTL3 or METTL14 expression reduced mRNA m6A levels, enhanced the growth and self-renewal of GSCs in vitro, and promoted the ability of GSCs to form brain tumors in vivo." (PMID 28297667, 2017).
bronchopulmonary dysplasia (2 papers, 2023 to 2025). Bronchopulmonary dysplasia is a chronic respiratory disease that results from complications related to lung injury during the treatment of infant acute respiratory distress syndrome in low-birth-weight premature infants or from abnormal lung development in older infants. "METTL3 aggravates pulmonary inflammation in bronchopulmonary dysplasia by mediating the m6A modification of ATG8, suppressing its expression, disrupting the GSDMD interaction, inhibiting autophagy, and inducing pyroptosis." (PMID 41105618, 2025).
colorectal adenocarcinoma (2 papers, 2022 to 2024). The most common type of colorectal carcinoma. "In addition, METTL3 is reported to maintain SOX2 expression in an m6A-dependent mechanism to facilitate the progression of colorectal adenocarcinoma." (PMID 35217651, 2022).
colorectal tumor (2 papers, 2022 to 2025). "Studies have shown that lactate derived from colorectal tumors directly mediates the lactylation of the methyltransferase‐like METTL3 zinc finger domain, which enhances the binding and catalytic activity of METTL3 on Janus kinase 1 (JAK1) mRNA, facilitating m6A modification." (PMID 40443721, 2025).
congenital heart defects (2 papers, 2024 to 2025). "This study reveals novel insights into DS cardiac pathology, highlighting the intricate role of METTL3 in DS congenital heart defects and presenting the m6A modification of SH3BGR as a potential therapeutic target." (PMID 39237501, 2024).
corneal endothelial dystrophy (2 papers, 2025). A corneal dystrophy (disease) that involves the corneal epithelium. "Upregulated Mettl3 has been associated with corneal endothelial dystrophy, while the inhibition of Mettl3 is implicated in the regulation of retinal ganglion cell ferroptosis in glaucoma." (PMID 41488750, 2025).
dental pulp inflammation (2 papers, 2018 to 2023). "Validation by qRT-PCR showed that the expression of methylases METTL14 and METTL3 was decreased, thus these two genes may play a key role in pulpitis." (PMID 37978362, 2023). "The results showed that there were significant differences in the genes ALKBH5, METTL14, METTL3, METTL16, RBM15B and YTHDF1 between normal group and the pulpitis group." (PMID 37978362, 2023). "However, YTHDF1, YTHDF3, METTL16 and METTL3 gene expression were not statistically different between the pulpitis group and the control group, and RBM15B, ZCCHC4 and ALKBH5 were up-regulated." (PMID 37978362, 2023).
E. coli infection (2 papers, 2022 to 2024). "METTL3 is a methyltransferase that accelerates m6A synthesis, which regulates viral replication and E. coli infection." (PMID 36362388, 2022).
glaucoma (2 papers, 2025). Increased pressure in the eyeball due to obstruction of the outflow of aqueous humor. "The downregulation of METTL3 expression and TGFβ/Smad3 signaling may improve the prognosis of glaucoma surgery." (PMID 40860194, 2025). "In addition, the upregulation of METTL3 could also promote TGF-β/Smad signaling to enhance viability, proliferation, and ECM deposition in both HTFs and rabbit models of Glaucoma filtration surgery (GFS)." (PMID 40860194, 2025).
Glucose intolerance (2 papers, 2025). Glucose intolerance (GI) can be defined as dysglycemia that comprises both prediabetes and diabetes. "Overexpression of METTL3 in cardiomyocytes also led to exacerbated glucose intolerance by Western diet, further showing the systemic effects of alterations in cardiac METTL3." (PMID 40272887, 2025).
Graves disease (2 papers, 2021 to 2023). Graves' disease is an autoimmune disorder that leads to overactivity of the thyroid gland (hyperthyroidism).It is caused by an abnormal immune system response that causes the thyroid gland to produce too much thyroid hormones. "Inducing m6A methylation in members of the SOCS family is the mechanism by which METTL3 is involved in the development of Graves' disease." (PMID 37784134, 2023). "The present study aimed to unveil the relationship of SOCS mRNA methylation induced by methyltransferase like 3 (METTL3) with Graves’ disease (GD)." (PMID 34616359, 2021). "Through a high-throughput microarray, METTL3 and cytokine signaling (SOCS) molecules were abnormally expressed in the CD4 T cells of Graves' disease." (PMID 37784134, 2023).
head and neck cancer (2 papers, 2019 to 2024). A primary or metastatic malignant neoplasm affecting the head and neck. "The multifaceted roles of METTL3 in regulating specific molecular signaling pathways across different types of cancers including head and neck cancer have been observed." (PMID 38966069, 2024). "Thus, we speculate that METTL3 may have diverse functions in tumor development depending on the location within head and neck cancer." (PMID 38966069, 2024).
hepatic (2 papers, 2024 to 2025). "In contrast, other m6A regulators, including METTL3, METTL14, WTAP, FTO, ALKBH5, YTHDC1, and YTHDC2, exhibited different protein expression patterns during ConA-induced hepatitis." (PMID 40092485, 2025).
hyperlipidemia (2 papers, 2022 to 2023). "Collectively, these results demonstrate that hepatocyte-specific Mettl3 knockin in mice accelerates diet-induced NAFLD-HCC by promoting hyperlipidemia and cell proliferation." (PMID 37586322, 2023).
inflammatory bone diseases (2 papers, 2023 to 2024). "Recent studies have unveiled that METTL3-mediated m6A modification is linked to inflammatory bone diseases, but the role of METTL3 can vary in different cells and tissues." (PMID 36674918, 2023). "Given that bone homeostasis is maintained by a dynamic balance between osteoblasts and osteoclasts, the effect of METTL3 on osteoblast biology in inflammatory bone diseases requires further investigation." (PMID 36674918, 2023). "Meanwhile, METTL3 knockdown could inhibit osteoclast differentiation and raise osteoclast apoptosis in inflammatory bone disease by promoting NOS2 mRNA stability in a YTHDF1-dependent manner." (PMID 38665846, 2024). "Inspired by this, METTL3-selective inhibitor application in BMSCs could be used to treat inflammatory bone diseases." (PMID 38665846, 2024).
intervertebral disc degeneration (2 papers, 2025). "In intervertebral disc degeneration (IVDD) models, KMT2A-mediated H3K4me3 upregulated methyltransferase-like 3 (METTL3), leading to reduced ATG4a mRNA stability via m6A modification, thereby suppressing autophagy in nucleus pulposus cells (NPCs) and accelerating SASP expression." (PMID 40814109, 2025).
kidney (2 papers, 2022). "The METTL3-mediated m6A modification level of TIMP2 mRNA may promote podocyte injury, apoptosis in glomeruli, and kidney inflammation through upregulating the Notch3 and Notch 4 signaling pathways." (PMID 36157472, 2022).
male infertility (2 papers, 2016 to 2022). The inability of the male to effect fertilization of an ovum after a specified period of unprotected intercourse. "With germ cell-specific inactivation of Nat10, both Mettl3 and Mettl14 can cause defects in spermatogenesis and male infertility." (PMID 35801907, 2022).
meningioma (2 papers, 2022 to 2023). A generally slow growing tumor attached to the dura mater. "We believed that IGFBP2 and METTL3 were survival-related m6A regulatory genes with critical prognostic value in meningiomas." (PMID 37910780, 2023). "Low expression of METTL3 and IGF2BP2 in meningioma cells (vs. normal meningioma cells) was also confirmed at the transcriptional and translational levels." (PMID 37910780, 2023). "In vitro experiments verified that the mRNA and protein expression levels of METTL3 and IGF2BP2 were lower in meningioma cells than in normal meningioma cells." (PMID 37910780, 2023). "In conclusion, two m6A methylated genes (METTL3 and IGF2BP2) were identified and a RiskScore methylation regulatory network was constructed, which can be considered prognostic factors for meningioma." (PMID 37910780, 2023). "In this study, METTL3 and IGF2BP2 were identified as crucial m6A genes for meningioma prognosis." (PMID 37910780, 2023). "In addition, low expression of METTL3 and IGF2BP2 in meningioma cells was verified by western blotting." (PMID 37910780, 2023). "Therefore, central regulators of m6A methylation (METTL3 and IGF2BP2) could potentially serve as novel therapeutic targets in meningioma." (PMID 37910780, 2023).
myelodysplastic neoplasms (2 papers, 2024 to 2025). "In myelodysplastic neoplasms (MDS) with DDX41 mutations, the nuclear m6A reader YTHDC1 interacts with the METTL3–METTL14 complex to maintain genomic stability." (PMID 40973767, 2025).
myocardial inflammation (2 papers, 2024 to 2025). "METTL3 and METTL14 deficiencies were induced to evaluate their effect on angiotensin II (Ang II)-induced myocardial inflammation and fibrosis." (PMID 38948064, 2024).
neuropathic pain (2 papers, 2021 to 2023). Chronic pain caused by damage to nerve fibers. "(2022) found that METTL3‐mediated m6A participated in neuropathic pain progression, and demonstrated that METTL3 could be a molecular markers of neuropathic pain patients." (PMID 36977205, 2023).
periodontal disease (2 papers, 2024). "In line with GO enrichment analysis, METTL3 deficiency led to a significant downregulation in inflammatory diseases including periodontal disease." (PMID 38696610, 2024).
rhabdomyosarcoma (2 papers, 2021 to 2024). A rare aggressive malignant mesenchymal neoplasm arising from skeletal muscle. "Here, we uncovered that EV71 infection enhanced METTL3 expression in interferon (IFN)-deficient Vero and IFN-proficient rhabdomyosarcoma (RD) cells by modulating transcription and post-translational modification, respectively." (PMID 39759074, 2024). "The increased METTL3 expression was also observed in EV71-infected rhabdomyosarcoma (RD) cells." (PMID 39759074, 2024). "Investigations show that the interaction between METTL3 and enterovirus 71 (EV71) nonstructural protein 2C or 3D may contribute to the cytoplasm localization of METTL3 in rhabdomyosarcoma (RD) cells." (PMID 34975810, 2021).